IL17A (interleukin 17A)
Diseases named in the same sentence as IL17A in open-access papers (continued):
Sharing a sentence is not in itself a finding about the gene and the disease.
psoriasis (continued). "Here, we established a psoriasis mouse model by intradermal injection of recombinant IL-17A into the dorsal skin of STAT3 transgenic mice." (PMID 37465147, 2023). "The cancer progressed after administration of secukinumab (a human circulating interleukin-17A monoclonal antibody) for psoriasis while continuing to receive pembrolizumab for another two cycles." (PMID 37978543, 2023). "In analogy to the successful targeting of the IL-17 axis in psoriasis, the anti-IL-17A antibody secukinumab and the IL-17R targeting antibody brodalumab were evaluated in clinical trials with IBD patients, but these trials unexpectedly had to be terminated." (PMID 38567057, 2023). "Anti-IL-17A BAs were most likely to induce hypertension (4.59%) and hepatic events (3.41%), and anti-IL-17A/F BAs were most likely to induce psoriasis and PSA (6.11%), followed by hypertension (4.82%)." (PMID 36817423, 2023). "This decline, which is instigated by IL-17A, underscores the profound link binding psoriasis to dyslipidemia." (PMID 38035065, 2023). "Other authors have reported reductions in the intima-media thickness of patients with severe psoriasis treated with an IL-17A inhibitor." (PMID 37533855, 2023). "HDL-C levels were reduced at week 52 after treatment with the anti-IL17A antibody IXE in patients with psoriasis." (PMID 36902720, 2023). "Its ability to attenuate the expression of IL-17A by Th17 and Tc17, a critical driver of psoriasis pathology, and inhibit the activation of γδ T cells further support its therapeutic potential in this disease." (PMID 37818377, 2023). "Previous research indicated that interleukin-17A (IL-17A), interleukin-22(IL-22), tumor necrosis factor-α (TNF-α), and interleukin-1α (IL-1α) were pro-inflammatory cytokines in psoriasis and linked with NF-κB signalling activation." (PMID 37636269, 2023). "Since this cytokine show synergy with TNF-α, IL-1α, IL-17A, and IL-22 in production of antimicrobial peptides, it is considered to be involved in pathogenesis of psoriasis." (PMID 37881433, 2023). "This hyperactivity spurs immune disequilibrium and psoriasis progression by magnifying histone H3 acetylation at the IL-17A promoter, which in turn bolsters Th17 and γδ T17 cell differentiation." (PMID 38035065, 2023). "Unfortunately, progression of colon cancer occurred after anti-IL-17 treatment was given to treat the psoriasis flare, supporting a role for IL-17A in antitumour immunity." (PMID 37211606, 2023). "Tregs from patients with psoriasis are able to differentiate into IL-17A producing cells after stimulation ex vivo." (PMID 36901778, 2023). "We examined the expression of cytokines previously reported to be involved in psoriasis, and found that IL17A, IL17F, IL26, CCL20, CXCL13, IL22, and IL23R were specifically expressed by Tc17 cells." (PMID 37308489, 2023). "We first studied how the immune cell numbers are changed in psoriasis skin after systemic IL-17A blockade, and how the immune cell number changes are reflected in total skin transcriptome." (PMID 37781383, 2023). "Our current study showed that the expression of IL23A in both mature and semimature DCs was decreased after systemic IL-17A blockade in posttreatment psoriasis lesional skin compared to pretreatment psoriasis lesional skin (p < 0.05)." (PMID 37781383, 2023). "Three IL-17A targeted monoclonal antibodies have been approved for psoriasis, psoriatic arthritis (PA) and ankylosing spondylitis (AS) treatment." (PMID 36646672, 2023). "CineMR dynamic images of patient 5 were acquired at baseline during a subacute phase of psoriasis-related myocardial injury (upper row) and at 18-months follow-up (lower row), after IL-17A monoclonal antibody therapy." (PMID 37373705, 2023). "Considering that psoriasis is a Th17-related inflammatory disease, we assessed the expression of Il17a and Il23a in mouse skin tissues." (PMID 38007430, 2023).
psoriasis (continued). "Secukinumab is a fully human anti-IL-17A monoclonal antibody approved for the treatment of PsA, psoriasis, and ankylosing spondylitis following the favorable results of several large RCTs." (PMID 37047357, 2023). "Results from qPCR show that the IMIQ conditions used to induce the psoriasis-like model were positive for inflammation induction, as all inflammatory cytokines (IL-17A, IL-17, IL-8, and IL-23) tested were significantly upregulated." (PMID 37896163, 2023). "Imiquimod is considered a TLR7/8 agonist, which can induce and intensify psoriasis in rat model via the activation of IL-23/IL-17A axis." (PMID 37010718, 2023). "Otherwise, DC-806 from DICE Therapeutics, Inc., an oral inhibitor of IL-17A that blocks its interaction with the cognate receptor, has been approved for a phase I clinical trial for psoriasis treatment." (PMID 37238999, 2023). "In psoriasis skin biopsy specimens, brepocitinib inhibited IL-17A/F and IL-12B expression more rapidly than tofacitinib (2 weeks vs. 4 weeks)." (PMID 36834806, 2023). "The resulting IL-17A is a particularly important effector molecule in the pathogenesis of psoriasis, since it inhibits keratinocyte differentiation and promotes their proliferation by downregulating Human Regenerating islet-derived protein 3-alpha (REG3A)." (PMID 37270497, 2023). "Secukinumab is a fully human IgG1κ MoAb that selectively binds to IL-17A with high affinity, and it has been proven effective for the treatment of psoriasis." (PMID 37029373, 2023). "Other DNA aptamers, M2 and M7 specific to IL-17A, were successfully used in the mouse model of psoriasis induced by imiquimod." (PMID 37238999, 2023). "Earlier, IL-23 secreted by these cells was shown to stimulate γδ T cells to secrete IL-17A, IL-17F, and IL-22 in psoriasis." (PMID 36645209, 2023). "Among the different cell compartments/types, we detected IL17A/F expression predominantly in the Th cell subset in skin samples of DD and psoriasis suggesting that Th17 cells are the main source of IL-17 in inflamed skin of patients with DD." (PMID 37978298, 2023). "Studies have reported that the CpG oligodeoxynucleotide induces psoriasis by expressing IL-17A through the NF-κB signaling pathway." (PMID 36835162, 2023). "Then, to investigate the mechanism of TGF-β induction, we stimulated healthy keratinocytes (NHEK) in vitro with a number of cytokines characterizing the psoriasis microenvironment including IL-1β, IL-6, IL-17A, IL-19, IL-22, IL-23, IL-26, and IFN-γ." (PMID 37391412, 2023). "These shifts are likely secondary to the direct effects of psoriasis-associated cytokines that we detected as upstream regulators of the keratinocyte pseudotime trajectory, especially IFN-γ, IL-17A, and TNF12." (PMID 37308489, 2023). "In these populations, another psoriasis population was identified that shared high levels of IL-17A and IL-17F, but also high levels of Th2 cytokines such as IL-4 and IL-13." (PMID 37834081, 2023). "IL-23, secreted by myeloid dendritic cells (mDCs), is increased when psoriasis persists or worsens and promotes Th17 cells differentiation to produce more IL-17A and IL-17F, which are pathophysiological evidence of psoriasis." (PMID 37298949, 2023). "IL-17A inhibits WNT signaling in bone (osteopenia and osteoporosis have been associated with psoriasis)." (PMID 36814601, 2023). "76.5% of IL17A+ T-cells, 61.4% of IL17F+ T-cells, and 100% of IL17A+IL17F+ T-cells were within the CD161+ T-cell cluster in pretreatment psoriasis lesional skin." (PMID 37781383, 2023). "Biological agents targeting IL-23 and IL-17A have shown excellent efficacy in treating psoriasis, implying that the IL-23/IL-17A axis is a major pathway involved in the pathogenesis of psoriasis." (PMID 37964882, 2023).
psoriasis (continued). "Upon discontinuation of IL-17A inhibitor and shifting to a broader T cell inhibitor-cyclosporine, our patient had control of both psoriasis and vitiligo and achieved 75% repigmentation after 3 months of oral cyclosporine without phototherapy." (PMID 36741377, 2023). "IL-23/IL-17A inflammatory axis is critical for the initiation and amplification of inflammatory responses in psoriasis." (PMID 36645209, 2023). "TNF-α and IL-17A both play a major role in inducing keratinocyte MAPK pathway activation in patients with psoriasis." (PMID 37686332, 2023). "We determined susceptibility of KC to VV and HSV-1 infection after exposure to representative cytokines prevalent in diverse inflammatory cutaneous diseases: IFNγ (lupus/AD; type 1), IL-4 and IL-13 (AD; type 2), IL-22 and IL-17A (psoriasis/AD, type 3)." (PMID 37298195, 2023). "In human, IL17A and several other family cytokines are also involved in the development of psoriatic arthritis, psoriasis and ankylosing spondylitis by inducing inflammatory cytokines and chemokines." (PMID 36838794, 2023). "It has been shown that IL-17A-activated PI3K/AKT/mTOR signaling contributed to the inflammatory response of psoriasis partly by inhibiting autophagy in keratinocytes." (PMID 36937834, 2023). "In contrast, imiquimod application, which has been used as a model of psoriasis, induced a more Il17a-dominant response, higher levels of AMPs, and enhanced protection against S. aureus." (PMID 37167061, 2023). "APM gels treated the psoriasis mouse model, and it shows a reduction in the proinflammatory cytokines (IL-8, IL-17A, IL-17F, and IL-23)." (PMID 37896163, 2023). "Despite the lower number, we found pseudotime trajectories between IL26+ and these IL17A+ T cells, indicating that the skin transition from IL26+ TH17 intermediates to IL-17A producers is a general principle that preferentially occurs in psoriasis." (PMID 37391412, 2023). "In psoriasis, it has been shown that selective inhibition of IL-23 blocks downstream production of IL-17A and IL-22 by Th17 and other cells." (PMID 37715294, 2023). "Among the various biological agents, ixekizumab is a humanised monoclonal antibody that blocks the biological activity of IL-17A, which exhibited high efficacy against psoriasis." (PMID 37799352, 2023). "Tumor necrosis factor-alpha (TNF-α), interleukin-1 alpha (IL-1α), interleukin-17A (IL-17A), interleukin-22 (IL-22), and oncostatin M (OSM) are closely associated with the pathogenesis of psoriasis." (PMID 36999136, 2023). "K14-IL17Aind mice develop psoriasis-like skin lesions due to constitutive, keratinocyte-derived overexpression of IL-17A." (PMID 38162658, 2023). "As the signal pathway for the induction of S100A7 mediated by IL-17, IκBζ is an essential regulatory factor in the pathogenesis of psoriasis through IL-17A and IL-17F-mediated actions." (PMID 37891988, 2023). "Psoriasis, a chronic inflammatory skin disease, is characterized by an immunological imbalance, resulting in the excessive secretion of IL-17A cytokine." (PMID 37818377, 2023). "The inhibitory effect of anti-IL-17A on psoriasis plays a significance role in the early histopathological, molecular and clinical treatment of psoriasis." (PMID 37029373, 2023). "We also treated HMEC-1 cells with psoriasis-related cytokines such as IL-17A, IL-22, IL-25, IFN-γ, TNF-α, and, VEGF-A, and among them, IFN-γ significantly upregulated the expression and secretion of IGFBP7 in HMEC-1 cells." (PMID 36917196, 2023). "IL-17, crucial in the psoriasis inflammatory cascade, and IL-23, a key regulator of IL-17A production, influence skin conditions by stimulating keratinocyte overproliferation and T cell-mediated inflammation." (PMID 38239358, 2023). "Based on the importance of IL-23/IL-17 axis, Bruton’s tyrosine kinase inhibitors can suppress imiquimod (IMQ)-induced psoriasis-like inflammation in mice through the regulation of IL-23/IL-17A in innate immune cells." (PMID 38139164, 2023).
psoriasis (continued). "Next, to examine the influence of skin inflammation levels, we measured the expression of inflammatory cytokines related to psoriasis and confirmed that Il17a, Tnf-α, and Cxcl1 mRNA expression in IMQ-induced lesions decreased after treatment with BZLF." (PMID 36950008, 2023). "Secukinumab, a monoclonal antibody specifically targeting interleukin-17A, was the first anti-interleukin-17A drug to be approved for the treatment of psoriasis by the Food and Drug Administration and the European Medicines Agency." (PMID 37176138, 2023). "CD8+CD103+ TRM cells release psoriasis-associated cytokines such as IFN-γ, IL-17A, and IL-22, while CD4+CD103+ TRM cells and CD8+CD103- TRM cells don’t secrete these cytokines." (PMID 37942312, 2023). "Most recently, these are drugs targeting the IL‐23/IL‐17A pathway which are reasonably effective in relieving skin symptoms of psoriasis." (PMID 36855912, 2023). "Secukinumab(SEC; AIN457; Cosentyx) is a fully human IgG1κ mAb that specifically targets IL-17A, which has been approved for the treatment of PsA, AS, psoriasis, moderate to severe plaque psoriasis (PSO), and axSpA." (PMID 37859999, 2023). "Considering the crucial function of these cytokines in the pathogenesis of inflammatory skin diseases, especially the role of IL-17A in psoriasis, AuNCs were employed to test their therapeutic effect on inflammatory skin disease models." (PMID 36839031, 2023). "Among them, the expression of IL17A is predominant in psoriasis skin lesions, and IL-17 increases the secretion of antimicrobial peptides (Defb4, Lcn2, S100a7, and S100a9) by keratinocytes." (PMID 37649889, 2023). "In conclusion, systemic IL-17A inhibition not only blocks the entire IL-23/T17 cell axis but also promotes regulatory gene expression in regulatory DCs in human psoriasis skin." (PMID 37781383, 2023). "Secukinumab was approved in 2015 for treatment of patients with psoriasis as the first IL-17A inhibitor, and nearly one year later it was also approved for PsA." (PMID 37029373, 2023). "Although IL-17A inhibition can effectively treat psoriasis and RA in the human study, IL-17A inhibitors have been rarely used to treat periodontitis." (PMID 37623290, 2023). "A recent case report describes the onset of vitiligo after the administration of adalimumab for psoriasis treatment, leading to its suspension and the initiation of secukinumab, an anti-interleukin-17A monoclonal antibody approved for psoriasis treatment." (PMID 38139134, 2023). "Subsequently, we will summarize the current knowledge around IL-17A and its five currently known homologues, namely IL-17B, IL-17C, IL-17D, IL-17E (also known as IL-25) and IL-17F, in relation to psoriasis with a focus on the most recent discoveries." (PMID 37283755, 2023). "Here we show that antibody-mediated inhibition of IL36R is sufficient to suppress imiquimod-induced psoriasis-like skin inflammation and represses the disease’s development in a model that depends on IL-17A overexpression in the skin." (PMID 38162658, 2023). "The expression of IL-17-driven inflammatory mediators (IL36G, S100A8, DEFB4A, and DEFB4B) in suprabasal keratinocytes was correlated with psoriasis severity and was downregulated by IL-17A blockade." (PMID 37781383, 2023). "The etiology of psoriasis is greatly influenced by the IL-23/IL-17A axis and, to a certain extent, reflects disease severity." (PMID 37920459, 2023). "Silencing of PARP2 in human keratinocytes prevented their hyperproliferation, maintained their terminal differentiation, and reduced their production of inflammatory mediators after treatment with psoriasis-mimicking cytokines IL17A and TNFα." (PMID 37351597, 2023). "Baicalin was found to mitigate the common symptoms of psoriasis, such as epidermal thickening, erythema, and desquamation induced by IL-17A, IL-22, and IL-23." (PMID 37371141, 2023). "At the same time, blockade of IL-17A by secukinumab leads to clinical, histologic, and molecular resolution of psoriasis." (PMID 37029373, 2023).
psoriasis (continued). "In patients with psoriasis, skin lesions, serum Th17 cell counts, and IL-17A levels were positively correlated with disease activity." (PMID 37920459, 2023). "In widely used treatments of psoriasis, IL17A inhibition is highly effective in preventing disease but application can rarely be stopped." (PMID 37144705, 2023). "A phase 2 clinical trial showed the effectiveness of treatment that inhibited IL-17A, which indicates the pathological role of IL-17A in mediating important inflammatory pathways in psoriasis." (PMID 38098004, 2023). "Clinical randomized trials targeting IL-17A and IL-17F antibodies in psoriasis have proven that these two cytokines can be used for therapeutic targets." (PMID 37942312, 2023). "In this study, we conducted an evaluation of alterations in hub genes subsequent to IL17A inhibition therapies in psoriasis." (PMID 37816883, 2023). "In 2016, anti-IL-17A monoclonal antibodies (mAbs), such as the IL-17 inhibitor secukinumab and the IL-17R inhibitor brodalumab, were both approved for the treatment of psoriasis." (PMID 38202170, 2023). "Based on our findings using the IMQ mouse model, we next investigated the effects of anti-IL36R antibody treatment in a genetic mouse model of IL-17A-driven psoriasis." (PMID 38162658, 2023). "AOA significantly reduced the expansion of IL-17A-producing Th17 cells and significantly induced the expansion of Foxp3+ Treg cells in psoriasis-like skin." (PMID 37649889, 2023). "The elevated plasma IL-17A detected in DCs, especially in patients with multiple sclerosis, arthropathic psoriasis and diverticular disease of the large intestine supports the previous findings showing its association with autoimmune inflammation." (PMID 37047248, 2023). "This phenomenon is likely due to the inflammation in the brain of offspring, induced by IL-17A, a key cytokine in psoriasis, from the mother because injection of IL-17A into fetal lateral ventricle can induce ASD-like phenotype in mice." (PMID 37920540, 2023). "Currently, the most successful therapies against psoriasis are biologic agents targeting IL17A or TNFα, but there are several safety concerns about the usage of such therapies, and there is a constant search for better-tolerated solutions." (PMID 37351597, 2023). "IL-17A, also known as IL-17, is a key cytokine in the pathogenesis of psoriasis and Th17 is its primary source." (PMID 36928592, 2023). "The conversion of Treg cells to IL-17A-secreting cells that have lost their suppressive function has been shown in several autoimmune diseases including psoriasis." (PMID 37818377, 2023). "In psoriasis, IL-17A-mediated inflammation contributes to acanthosis and plaque formation; therefore, its blocade via IL-17 inhibitors leads to clinical remission." (PMID 37631384, 2023). "Th17-derived proinflammatory cytokines (IL-17A, IL-17F, IL-21, IL-22, and IL-26) have a critical role in the pathogenesis of several autoimmune diseases such as psoriasis, multiple sclerosis, rheumatoid arthritis, and inflammatory bowel disease." (PMID 37495626, 2023). "Adiponectin has also been shown to exert its anti-inflammatory effects in psoriasis patients by restoring the balance between Th1-Th17/Th2 and inhibiting IL-17A synthesis." (PMID 36675592, 2023). "There were limited studies on establishing a psoriasis model through IL-17A injection, in contrast to IL-23 which has become a classic model for psoriasis due to its ability to stimulate Th17 cell activation via secretion from antigen-presenting cells." (PMID 37465147, 2023). "For example, CD103+TRM cells can release IL-17A in epidermis of subsided psoriasis and are related to early recurrence." (PMID 37942312, 2023). "IL-17A blockade reduces type 17 T-cell signatures in psoriasis lesional skin at single-cell cluster levels." (PMID 37781383, 2023). "Here we described a woman who developed de novo vitiligo after 4 months of IL-17A inhibitor treatment for psoriasis and psoriatic arthritis." (PMID 36741377, 2023).